AHR (aryl hydrocarbon receptor)
Diseases named in the same sentence as AHR in open-access papers (continued):
Sharing a sentence is not in itself a finding about the gene and the disease.
colitis (continued). "However, no significant changes in AhR mRNA levels were observed between CECs cocultured with microbiota from control mice and those cocultured with colonic microbiota from colitis mice." (PMID 40410944, 2025). "Cumulatively, it was identified that I3C attenuated acute colitis through activating AhR, improving gut microbiota and mitigating inflammation, whereas DIM inhibited inflammation and angiogenesis, revealing that both I3C and DIM can be considered as a potential agent against colitis." (PMID 40094833, 2025). "Moreover, dietary supplementation with an AhR pro-ligand, I3C, showed a protective effect in AhRfl/fl, but not AhR△mye colitis model mice, highlighting the critical role of macrophage AhR in regulating intestinal inflammation." (PMID 39113799, 2024). "Furthermore, The AhR ligands TCDD, Norisoboldine (NOR), and FICZ have been shown to alleviate colitis symptoms by activating AhR pathways." (PMID 39767818, 2024). "Furthermore, ILA could protect against tumorigenesis by regulating macrophage differentiation in CAC mice; the AhR antagonist largely abrogated the effects of B. breve and ILA in relieving colitis and tumorigenesis." (PMID 38773969, 2024). "However, our current study, adding to our previous report, suggests that while IL-22 production increases in response to colitis induction, AhR does not appear to regulate this cytokine to promote any protective effects." (PMID 39229279, 2024). "Aryl hydrocarbon receptor (AhR) signalling in the gut epithelia was shown to be indispensable for the induction and colonic accumulation of regulatory T cells (Tregs), following treatment with Indigo naturalis, which ameliorates the disease in UC patients and in a DSS-induced colitis mouse model." (PMID 38534321, 2024). "Our results showed that IAA may alleviate colitis by modulating the intestinal microbiota and does not rely exclusively on the activation of AhR in DSS mice." (PMID 38504383, 2024). "Therefore, we investigate if AhR orchestrates the effects of combined butyrate and VD3 on cytokines response (IL-17A and IL-22), antimicrobial peptides (LL-37), and tight junction proteins expression to block the invasion of Salmonella in colitis mice." (PMID 36678175, 2023). "Although much of the protective role of AHR in the gut has been attributed to its activation by dietary and/or microbiota derived ligands, TCDD also ameliorates DSS- and 2,4,6-trinitrobenzenesulfonic acid (TNBS)-induced colitis by reducing inflammation and promoting regulatory immune cells." (PMID 35055106, 2022). "Transferring the intestinal flora from CARD9-null mice to wild-type germ-free mice is proven to promote colitis and reduce IL-22 production, because the microbiota in CARD9-null mice is unable to metabolize tryptophan into the ligands of aryl hydrocarbon receptor (AHR)." (PMID 35619716, 2022). "Thus far, the requirement of basal level of CYP1A1 for AhR-mediated protective activities against colitis has not been reported." (PMID 36159798, 2022). "Whether resveratrol’s suppression of colitis is independent of AHR and rather due to its more general antioxidant and anti-inflammatory properties has not been experimentally determined." (PMID 35055106, 2022). "Given that AhR signaling is a pivotal component of the immune response at barrier sites, the interplay between the metabolites and AhR has a significant influence on maintaining intestinal homeostasis, inhibiting infection with pathogens, and ameliorating DSS-induced colitis." (PMID 34439208, 2021). "A novel AhR activator is 1,4-dihydroxy-2-naphthoic acid (DHNA), a precursor of vitamin B12 produced by Propionibacterium freudenreichii ET-3, inducing intestinal anti-microbial protein synthesis, altering GM composition and inhibiting murine DSS-induced colitis." (PMID 34122415, 2021).
colitis (continued). "The administration of urolithin A mitigates barrier dysfunction and colitis development in the mouse model of 2,4,6-trinitrobenzene sulfonic acid-induced colitis; this protective effect is attenuated in mice lacking either Nrf2 or AhR." (PMID 33968085, 2021). "Moreover, AhR-expressing Treg cells have enhanced in vivo suppressive activity compared with Treg cells lacking AhR expression in a T cell transfer model of colitis, highlighting a central role of AhR in microbiota-induced pTreg cell generation and function." (PMID 31921097, 2019). "It is therefore possible that failure of UroA/UAS03 mediated protective activities against colitis in AhR−/− mice may not provide conclusive evidence for AhR role." (PMID 30626868, 2019). "Thus, we propose that FMT could increase the secretion of anti-inflammatory cytokines by activating AhR signaling in Treg cells of colon tissues, which are responsible for FMT-reduced colon inflammation." (PMID 30197631, 2018). "These activities of AhR help ensure that commensal bacteria outcompete pathogenic bacteria in the gut microbiota, and the absence of AhR increases the severity of DSS-induced colitis and response to Citrobacter rodentium infection (a model of human enteropathogenic E. coli infections)." (PMID 27102537, 2016). "Intestine tissue from patients with IBD expressed significantly less AhR than controls, Experimental animal models of colitis show that attenuation of AhR receptor expression resulted in a protective effect during DSS-induced colitis, while the absence of AhR exacerbated the disease." (PMID 24905409, 2014). "Also, based on the previous report that AhR activation leads to Treg differentiation in a ligand-specific fashion, we next determined whether TCDD induces Tregs in DSS-induced colitis." (PMID 21858153, 2011). "Although prior studies indicate that HQD alleviates colitis symptoms by modulating gut microbiota and that AhR signaling is critically involved in ISC regulation, whether HQD ameliorates colitis through the microbiota–tryptophan metabolism–AhR–ISC axis remains to be elucidated." (PMID 41530817, 2026). "Moreover, following the activation of AHR by FICZ, DCs become more efficient inducers of Tregs, and the adoptive transfer of such regulatory DCs to mice with 2,4,6-trinitrobenzenesulfonic acid (TNBS)-induced colitis alleviates the severity of the ongoing inflammation." (PMID 38674118, 2024). "However, what was not established in this previous report was whether AhR was specifically driving these observations during I3C treatment and colitis, particularly as it related to increased IL-22 production by ILC3s and regulation of the gut microbiome." (PMID 39229279, 2024). "Quercetin, a clear AHR agonist, could shorten the course of chronic DSS colitis in an AHR-dependent manner KAR, a flavonoid derived from Sophora flavescens, is an effective treatment of visceral hypersensitivity in IBS, and it regulates the development of IBS through macrophage-intrinsic AHR." (PMID 37179416, 2023). "However, FICZ-mediated rescue of DSS-colitis in vivo may not exclusively be attributed to the intrinsic role of AhR in IECs, as the activation of AhR also affects immune cells in the intestinal tissue." (PMID 36875083, 2023). "Additionally, UroA/UAS03 failed to mitigate TNBS-induced colitis in mice lacking AhR." (PMID 30626868, 2019). "When we analyzed the expression of anti‐inflammatory cytokine IL‐10, I3C increased its mRNA levels both in WT colitis mice and AhR∆IEC colitis mice thereby suggesting that the ability of I3C to induce IL‐10 was independent of AhR expression on CECs." (PMID 40410944, 2025). "Instead, when the AHR is absent, the number of IELs is decreased, and the burden of intestinal bacteria is increased, which promotes dextran sulfate sodium (DSS)-induced colitis." (PMID 37179416, 2023).
colitis (continued). "Besides, AhR activation by several endogenous ligands, including 6-Formylindolo(3,2-b)carbazole (FICZ), kynurenine and 1,25-dihydroxyvitamin D3 (VD3), could inhibit the NF-κB signaling pathway and reduce IL-1β expression in periodontitis, glioblastoma and colitis." (PMID 36721094, 2023). "This phenotype was independent of TNBS-induced colitis but mediated by AhR activity, as IgA levels were comparable between TCDD- and control-fed AhR-/- mice." (PMID 36875083, 2023). "Independent of SHP2, AhR activation by the tryptophan derivative 6-formylindolo (3, 2-b) carbazole (FICZ) has indeed shown to ameliorate DSS-induced colitis and exclusively promote the MAPK/ERK-dependent differentiation of GCs." (PMID 33777031, 2021). "The correlation between activation of AhR, repression of glycolysis, regulation of NAD+/SIRT1/SUV39H1/H3K9me3 signals, induction of Treg cells, and eventual anti-colitis effect of NOR were validated by using CH223191 and HK2 plasmid." (PMID 29449535, 2018). "Another in vivo study found that Beta-naphthoflavone (beta NF), a non-toxic agonist of AhR, suppressed the pathogenesis of the DSS-induced colitis through the inhibition of pro-inflammatory cytokine production, such as TNF-a and IL6." (PMID 24905409, 2014). "Finally, in Abx-generated pseudo-germ-free mice, HQD failed to up-regulate AhR signaling or to promote Lgr5+ ISC differentiation, and it no longer offered protection against DSS-induced colitis." (PMID 41530817, 2026). "Before and after the colitis induction, mice were oral gavage with active vitamin D3 0.2 μg/25 g mice (VD3) and/or postbiotics propionate (PP), in the absence of the presence of intraperitoneal injection of AhR inhibitor for 4 and 7 days, respectively." (PMID 36672703, 2023). "Finally, the correlation between NOR-mediated activation of AhR, repression of glycolysis, regulation of NAD+/SIRT1/SUV39H1/H3K9me3 signals, induction of Treg cells, and remission of colitis was confirmed in mice with DSS-induced colitis by using CH223191 and HK2 plasmid." (PMID 29449535, 2018). "HQD could alleviate DSS-induced colitis through microbiota-derived indoles that activate AhR and, directly or via IL-22, drive ISC differentiation; however, this attractive mechanistic framework is not unique to HQD—probiotics or synthetic AhR agonists can exploit the same pathway." (PMID 41530817, 2026).
breast carcinoma (276 papers, 2006 to 2026). "Higher levels of KYNA are also associated with a lower risk of breast cancer, but this is contradicted by the fact that the Trp-AhR pathway promotes tumor cell growth (mentioned in Section ‘TDO and the Reproductive System’)." (PMID 41282989, 2025). "Particularly relevant for basal-like breast cancer (BLBC) and BRCA1-associated breast cancers, studies show that ROS levels correlate with the expression and activity of the transcription factor aryl hydrocarbon receptor (AhR)." (PMID 39857438, 2025). "Previous studies have reported associations between AHR single nucleotide polymorphisms (SNPs) and breast cancer risk." (PMID 40646277, 2025). "Treatment with DATS significantly inhibited (p < 0.0001) AhR expression, implicated in the development and progression of breast cancer." (PMID 38276538, 2024). "Simultaneously, DEHP has been reported to not only mediate drug resistance by activating the vinculin/aryl hydrocarbon receptor (AhR)/ERK signaling pathway but also enhance susceptibility to breast cancer by upregulating the Esr1/HDAC6 pathway in female rats." (PMID 38341560, 2024). "Our data reveal long-term pharmacological inhibition of AHR by BAY2416964 closely resembles AHR loss in a mouse model of breast cancer." (PMID 39450255, 2024). "The analysis further revealed that MCU, alongside genes commonly mutated in breast cancer, demonstrated elevated expression levels comparable to key T cell regulators such as AHR, ID2, and TBFb1." (PMID 38632642, 2024). "Further, in estrogen receptor (ER)-positive breast cancer, AhR signaling increased antiapoptotic x-linked inhibitor of apoptosis (XIAP) and superoxide dismutase type 1 in two cell lines, leading to apoptotic resistance." (PMID 38339226, 2024). "Here, we investigated the effects of short-term (<24 h) and long-term (>6 weeks) treatment with BAY2416964 and compared them with AHR loss in a PyMT mouse mammary tumor cell line." (PMID 39450255, 2024). "Here we compared the effect of BAY2416964 treatment with AHR loss on cell growth, invasion and gene expression in PyMT mouse mammary cancer cells." (PMID 39450255, 2024). "In a human breast cancer cell line, the constitutive expression of AhR via the introduction of a mutation can downregulate CTNNB1." (PMID 37232717, 2023). "High AhR expression in breast cancer cells is significantly correlated with ROS build-up, which causes AhR to translocate into the nucleus and enhances its transcriptional activity." (PMID 37238995, 2023). "Several studies have also linked expression of the AhR with inflammatory response pathways in breast cancer cells." (PMID 36428667, 2022). "In a mouse model of BRCA1-associated breast cancer, AhR was found to transcriptionally induce the EGF receptor ligand, Amphiregulin, driving tumor growth and macrophage infiltration." (PMID 36588678, 2022). "This study also found a significant correlation between AhR activity and “cancer stem cell- and migration/invasion-associated gene sets” in an analysis of 79 human breast cancer cells lines and more than 1,850 human breast cancers." (PMID 36588678, 2022). "Kyn produced by fibroblast induced the formation of E-cadherin-aryl hydrocarbon receptor (AhR)-sphase kinase-associated protein 2 complex, reducing E-cadherin and enhancing breast cancer invasiveness." (PMID 35406118, 2022). "The activation of the AhR signaling pathway via environmental pollutants including dioxins and PAHs has been associated with the development of breast cancer." (PMID 36588678, 2022). "High expression of AhR in breast cancer has been associated with signaling pathways related to metabolism and insulin-like growth factor (IGF) signaling." (PMID 34094928, 2021). "Genetic and metabolic alterations in basal-like and BRCA1-associated breast cancer can lead to chronic high levels of ROS, increasing the level of AhR protein and its transcriptional activity." (PMID 33451095, 2021).
breast carcinoma (continued). "In fact, AhR deficiency as well as AhRR overexpression resulted in an accumulation of these DNA lesions in both breast cancer cell-lines, suggesting a regulatory function of AhR in DSB repair." (PMID 33763068, 2021). "The aryl hydrocarbon receptor (AHR) pathway has been linked to the induction of breast cancer and to gene activation supporting the progression of this disease." (PMID 32814815, 2020). "In ERα-positive breast cancer, tamoxifen resistance is associated with AhR activation, whilst its efficacy is modulated by CYP2C19 alleles." (PMID 35582450, 2020). "The AhR/CYP1A1 pathway participates in carcinogenesis by mediating stem properties, the formation of mammospheres, expansion of breast cancer stem cells, and the transcriptional activity of AhR is mainly implicated in such effects." (PMID 32670863, 2020). "In conclusion, TFPI-2 mRNA levels were upregulated by miR-494 in MCF-7 breast cancer cells most likely by an indirect association where miR-494 targeted the transcription factors AHR and ELF-1." (PMID 32132611, 2020). "Various animal experimental data have provided substantial support for an association between abnormal AhR expression/function and breast cancer." (PMID 29320557, 2018). "Oestrogen-positive breast cancer shows a strong association between AhR regulation and cancer metastasis." (PMID 28195146, 2017). "For instance, in MCF7 human breast cancer cells, AhR activation was linked to silencing of BRCA1 by recruitment of DNA methyltransferases to its promoter region." (PMID 27243009, 2016). "The first objective of this study was to investigate the association between AhR expression and/or activation and Brca-1 promoter methylation status in mammary tumors." (PMID 26715507, 2015). "This led us to conclude that AhR has the capacity to influence key cellular process associated with breast cancer aggressiveness (promotion/progression)." (PMID 24932473, 2014). "Numerous studies have implicated the aryl hydrocarbon receptor (AhR) as a potential therapeutic target for several human diseases, including estrogen receptor alpha (ERα) positive breast cancer." (PMID 24885022, 2014). "In the present study we investigated the genes that are differentially regulated by AhR and are controlling cellular processes linked to breast cancer." (PMID 24932473, 2014). "Conversely, fibroblast-secreted kynurenine promotes the formation of the E-cadherin/Aryl hydrocarbon receptor (AhR)/S-phase kinase-associated protein 2 (Skp2) complex, resulting in degradation of E-cadherin to increase breast cancer invasiveness." (PMID 25060643, 2014). "The AHR/ARNT heterodimer has been implicated as having importance in ER positive breast cancer and has been shown to directly associate with estrogen receptors ER-alpha and ER-beta." (PMID 22709873, 2012). "Our region on chromosome 7 contains the AHR gene that has been associated with breast cancer risk, and IL6, which contains a marker associated with increased risk for breast carcinoma." (PMID 23190577, 2012). "One of the main causes for AhR overexpression in these MCF breast cancer cells appears to be the loss of ERalpha functions." (PMID 19604390, 2009). "Our previous studies demonstrated that, in other cell types, galangin is a potent inhibitor of the aryl hydrocarbon receptor (AhR), an environmental carcinogen-responsive transcription factor implicated in mammary tumor initiation and growth control." (PMID 16569260, 2006). "Taken together, in response to the “signal(s)” from primary tumor cells, the changes of AHR in lung macrophages could be associated with PMN formation during breast cancer progression." (PMID 39690159, 2024). "B[a]P is a main ligand of AhR that directly binds to the receptor and induces its biological effects associated with carcinogenesis in cancer and the development and progression of breast cancer." (PMID 38276538, 2024). "AhR is implicated in both breast cancer progression and drug resistance." (PMID 38792249, 2024).